ALB (albumin)
Diseases named in the same sentence as ALB in open-access papers (continued):
Sharing a sentence is not in itself a finding about the gene and the disease.
adenoid cystic carcinoma (1 paper, 2022). A malignant tumor arising from the epithelial cells. "Patients and Methods: This retrospective cohort study included all patients treated for a head and neck adenoid-cystic carcinoma between 1993 and 1 June 2019 with available pretherapeutic albumin values and clinical follow-up data." (PMID 35052870, 2022). "The aim of this study is to assess the potential prognostic value of serum albumin in patients with head and neck adenoid-cystic carcinomas." (PMID 35052870, 2022).
adrenocortical tumor (1 paper, 2023). "A nanoparticle formulation based on curcumin and lipoic acid crosslinked to human serum albumin has been demonstrated to intensify the in vitro antitumor effects of Doxorubicin against H295R adrenocortical tumor cells and demonstrated the effective and fast uptake of the nanoparticle." (PMID 37109643, 2023).
age (1 paper, 2024). A temporal measurement of the time period elapsed since an identifiable point in the life cycle of an organism. "Low ALP, LDH and albumin levels are associated with decreased liver metabolic function in aging and may correlate with age‐related chronic diseases." (PMID 37897241, 2024).
AIDS-related lymphoma (1 paper, 2022). "In conclusion, serum albumin at diagnosis is an independent prognostic factor for overall survival in AIDS-related lymphoma." (PMID 35717275, 2022).
allergic conjunctivitis (1 paper, 2013). "In cases of allergic conjunctivitis tear levels of serum albumin reach serum levels rapidly, indicating a direct leak from inflamed vessels." (PMID 23308132, 2013).
alveolitis (1 paper, 2021). "After ten days of infecting mice with virus through intranasal inoculation, we noticed a considerable reduction in alveolitis in the mice that were infected with rCD66c bound IAV as compared to mice treated with virus alone or virus incubated with protein control Bovine Serum Albumin (BSA)." (PMID 33919410, 2021).
anaplasmosis (1 paper, 2020). "However, a decrease in serum protein, albumin, and globulin levels has been reported in cattle with anaplasmosis." (PMID 33061222, 2020).
aortic atherosclerosis (1 paper, 2025). A atherosclerosis that involves the aorta. "Among patients with type B AAD, those in the high-WBC group were younger, had ahigher incidence of smoking and aortic atherosclerosis (AS), and had higheraverage heart rate (HR), SBP, diastolic blood pressure (DBP), and albumin levelcompared to those in the low-WBC group." (PMID 40351700, 2025).
arteriolosclerosis (1 paper, 2024). The thickening of the wall of the small arteries and arterioles. "Based on the univariate analysis, the binary logistic regression analysis was conducted on the six variables (i.e., age, serum uric acid level, eGFR, serum albumin, TA/IF, and the presence of arteriolosclerosis) with significance in the univariate analysis." (PMID 38548844, 2024). "Binary logistic regression analysis was performed on five variables that showed significant associations in univariate analysis: age, serum uric acid level, eGFR, serum albumin, and presence of arteriolosclerosis." (PMID 38548844, 2024). "Compared with the non-GIL group, the GIL group exhibited were older, had enhanced serum uric acid, serum albumin, and an increased prevalence of tubular atrophy/interstitial fibrosis (TA/IF), arteriolosclerosis, and low eGFR levels (P < 0.05)." (PMID 38548844, 2024). "However, in the GIL group age, serum uric acid level, serum albumin, the prevalence of renal tubular atrophy/interstitial fibrosis, and prevalence of arteriolosclerosis was significantly higher in the GIL group than the non-GIL group (P < 0.05)." (PMID 38548844, 2024).
arthus reaction (1 paper, 2020). A localized vasculitis resulting from deposition of antibody-antigen complexes. "LZ-8 and FIP-fve could suppress bovine serum albumin-induced Arthus reaction and systemic anaphylaxis reaction in mice, which was explained by reduction of antibody production." (PMID 33015115, 2020). "Fip-vvo significantly reduced the production of bovine serum albumin-induced Arthus reaction in mice in vivo, whereas there was no apparent effect in the prevention of systemic type I anaphylaxis reactions." (PMID 33015115, 2020).
ascending aorta dilatation (1 paper, 2020). "This study aimed to determine plasma thiol, disulphide, and serum ischemia-modified albumin (IMA) levels and ferroxidase activity in patients with ascending aorta dilatation (AAD) in comparison to those without AAD and to evaluate the predictive value of these oxidative stress parameters for AAD." (PMID 32421280, 2020).
aseptic loosening (1 paper, 2022). A failure of the bond between an implant and bone in the absence of infection. "The levels of serum total protein and GLO in the PJI group were significantly higher than those in the aseptic loosening group, and the levels of ALB and AGR in the PJI group were significantly lower than those in the aseptic loosening group." (PMID 35907808, 2022).
astrocytoma (1 paper, 2022). "Human EA.hy926 endothelial (and U87MG astrocytoma) cells were highly vulnerable to increasing Cu–albumin challenges and demonstrated prominent mitochondrial structural and functional deficits." (PMID 34857647, 2022).
autoimmune bullous skin disease (1 paper, 2025). An autoimmune disease characterized by blisters on the skin. "albumin antibodies have been observed in a subset of SLE or autoimmune bullous skin disease patients." (PMID 40609794, 2025).
autoimmune gastritis (1 paper, 2020). Inflammation of the body fundic mucosa of the stomach. "The results showed that thiol/disulfide homeostasis in patients with autoimmune gastritis caused an increase in ischemia modified albumin and disulfide whereas a decrease in thiols." (PMID 31814373, 2020). "The aim of this study is to examine dynamic thiol/disulfide homeostasis and ischemia modified albumin levels, and to analyze the association between thiol/disulfide homeostasis and gastric emptying time in autoimmune gastritis." (PMID 31814373, 2020). "Thiol/disulfide homeostasis tests and ischemia modified albumin levels were determined in 50 autoimmune gastritis patients and 53 healthy subjects." (PMID 31814373, 2020).
autonomic dysreflexia (1 paper, 2026). A syndrome associated with damage to the spinal cord above the mid thoracic level (see SPINAL CORD INJURIES) characterized by a marked increase in the sympathetic response to minor stimuli such as bladder or rectal distention. "Fully adjusted models included age, comorbidities, inflammatory status, functional independence, injury duration, age at injury, autonomic dysreflexia, body mass index (BMI), HDL, and testosterone-binding factors, including albumin." (PMID 42068005, 2026).
axonal neuropathy (1 paper, 2024). Any nerve disorder affecting the axon of a nerve. "The presence of albumin-cytological dissociation and axonal neuropathy confirmed the diagnosis of acute inflammatory demyelinating polyneuropathy (AIDP)." (PMID 38420060, 2024).
bile duct neoplasm (1 paper, 2020). A benign or malignant neoplasm that affects the intrahepatic or extrahepatic bile ducts. "There are several reports on aberrant expression of albumin; it could be used to distinguish bile duct neoplasm from other metastatic adenocarcinoma 46-48." (PMID 32368289, 2020).
Binswanger disease (1 paper, 2020). "Reduced MMP-2 index and elevated albumin index were also able to reliably predict the development of Binswanger disease in VCI." (PMID 32340195, 2020).
blood disease (1 paper, 2023). A disease that occurs in the blood. "In these alternative solutions, recombinant albumin not only has the advantage of being able to be mass-produced at a lower cost, but also avoids the risk of transmission of blood diseases." (PMID 37113668, 2023).
bowel dysfunction (1 paper, 2024). Any disease in which the causes of the disease is a perturbation of the lower digestive tract leading to its dysfunction. "Reduced levels of serum albumin are linked to intestinal wall edema, which will lead to bowel dysfunction." (PMID 39044193, 2024).
brain abnormalities (1 paper, 2024). "A third study excluded from full text review identified increases in levels of NSE and ischemia-modified albumin (IMA) for SGA infants with brain abnormalities compared to SGA infants without brain abnormalities." (PMID 38966491, 2024).
bronchiolitis (1 paper, 2019). Inflammation of the bronchioles characterized by swelling of the bronchioles and mucus accumulation. "In this secondary analysis of a cohort of 1016 infants hospitalized for bronchiolitis, low serum albumin was statistically significantly associated with a higher risk of apnea during the hospitalization." (PMID 31314114, 2019). "This secondary analysis of the 35th Multicenter Airway Research Collaboration cohort study investigates whether serum albumin levels are associated with apnea in infants hospitalized for bronchiolitis." (PMID 31314114, 2019). "Is serum albumin level associated with the risk of apnea in infants with bronchiolitis?" (PMID 31314114, 2019). "Second, the mechanism for low albumin levels in bronchiolitis with apnea remains uncertain, despite the intriguing animal data about neurogenic inflammation." (PMID 31314114, 2019). "The mechanism of low albumin levels in bronchiolitis is uncertain." (PMID 31314114, 2019). "Fourth, the association between albumin and apnea may not be generalizable beyond the study population of infants hospitalized for bronchiolitis." (PMID 31314114, 2019). "Until further research is completed, we do not recommend clinicians check albumin levels in infants with bronchiolitis unless otherwise clinically indicated." (PMID 31314114, 2019). "Thus, although decreased synthesis of albumin from poor nutrition may be part of the mechanism of low serum albumin levels in bronchiolitis, it is not the only factor." (PMID 31314114, 2019).
Buerger disease (1 paper, 2019). "Furthermore, higher albumin levels in male patients (31.1 for males versus 27.4 for females; P = 0,01) and increased occurrence of Buerger disease among males (P = 0.018) might explain favourable mortality rates in males." (PMID 31722699, 2019).
Burkitt lymphoma (1 paper, 2022). A rare form of malignant mature B-cell non-Hodgkin lymphoma. "To further investigate the role of surface albumin in peptide binding, we have used the human Burkitt’s lymphoma cell line, Ramos, as a control that does not bind to the NW peptide." (PMID 35457098, 2022).
C. perfringens infection (1 paper, 2020). "An Arg × infection interaction was also found for ALB levels in the blood plasma of turkeys (P < 0.001): C. perfringens infection increased ALB levels at the lowest and medium Arg content (Arg90 and Arg100, respectively), but not at the highest Arg content (Arg110)." (PMID 32264939, 2020). "Clostridium perfringens infection increased the levels of MDA (P = 0.005) and ALB (P < 0.001), and GPx activity (P < 0.001), and decreased the levels of TG (P < 0.001) and UA (P < 0.001), and ALT activity (P < 0.001)." (PMID 32264939, 2020). "Similarly to Experiment 1, C. perfringens infection increased the levels of MDA (P = 0.007) and ALB, and GPx activity (both P < 0.001), and decreased the levels of TG (P = 0.009) and UA, and ALT activity (both P < 0.001)." (PMID 32264939, 2020).
cadmium poisoning (1 paper, 2025). Poisoning occurring after exposure to cadmium compounds or fumes. "Cadmium poisoning is also associated with a decline in serum albumin levels, which leads to an increase in the bioavailable free form of cadmium, exacerbating tissue damage in organs where it accumulates." (PMID 40278162, 2025).
CAEBV infection (1 paper, 2022). "LU Gen and his colleagues showed that platelet count and decreases in albumin are potential risk factors for a poor prognosis of CAEBV infection." (PMID 35187008, 2022).
carcinosarcoma (1 paper, 2012). A malignant tumor composed of a mixture of carcinomatous and sarcomatous elements. "The contrast capabilities of the proposed algorithms on bi-exponential data are also discussed and demonstrated with an in vivo two photon fluorescence lifetime imaging data of FITC-albumin labeled vasculature of a P22 rat carcinosarcoma." (PMID 22778606, 2012). "In vivo two photon fluorescence lifetime imaging data of FITC-albumin labeled vasculature of a P22 rat carcinosarcoma (BD9 rat window chamber) are used to test how different algorithms perform on bi-decay data." (PMID 22778606, 2012).
cardiac interstitial fibrosis (1 paper, 2017). "We identified that MAP and DBP were both correlated with albumin excretion, glomerular hypertrophy and renal interstitial fibrosis in male offspring, but were not correlated with cardiac interstitial fibrosis." (PMID 28811528, 2017).
cardiac tamponade (1 paper, 2025). Acute compression of the heart caused by increased intrapericardial pressure due to the collection of blood or fluid in the pericardium from rupture of the heart, penetrating trauma, or progressive effusion. "The Fit.RF model incorporated eight variables:mesenteric malperfusion, cardiac tamponade, D2, INR, platelet count (Plt),albumin levels, CPB time, and intraoperative red blood cell transfusion." (PMID 40351672, 2025).
catalepsy (1 paper, 2008). A nervous system disorder characterized by diminished responsiveness and consciousness, and rigidity of the body. "Animal studies involved use of histamine induced bronchoconstriction in guinea pigs, egg albumin induced passive paw anaphylaxis in rats and haloperidol-induced catalepsy in mice." (PMID 20046767, 2008).
central nervous system infections (1 paper, 2024). "Additionally, a retrospective study has also demonstrated that low albumin levels increase the risk of central nervous system infections and mortality." (PMID 38481940, 2024).
cerebral embolism (1 paper, 2025). "This study explored the association between inflammatory biomarkers—C-reactive protein to albumin ratio (CAR), platelet to lymphocyte ratio (PLR), and neutrophil to lymphocyte ratio (NLR)—and the prognosis of patients with cardiogenic cerebral embolism (CCE)." (PMID 40599820, 2025).
cerebral lesions (1 paper, 2010). "As an example of this hypothesis, we have recently reported that albumin is nitrated in newborns who suffered perpartal asphyxia and that the levels of plasma nitroalbumin are highly correlated to the severity of the ensuing cerebral lesions." (PMID 20383279, 2010).
Chagas disease (1 paper, 2022). A parasitic infection caused by Trypanosoma cruzi. "In a study conducted on children under 13 years of age in the acute phase of Chagas disease in an endemic area of Bolivia, a significant increase in alpha-2-macroglobulin and C-reactive protein concentrations was observed; this mobilization probably directly affected the albumin levels." (PMID 35371021, 2022).
chorioamnionitis (1 paper, 2023). A morphologic finding indicating inflammation of the fetal sac membranes. "Multivariable binary logistic regression analysis showed that maternal chorioamnionitis, multiple births, use of indomethacin, use of inotropic agents, plasma albumin level, and PDA size were independent risk factors influencing the efficacy of NSAIDs." (PMID 37082702, 2023). "Multivariable binary logistic regression analysis showed that maternal chorioamnionitis, multiple births, use of indomethacin, use of inotropic agents, plasma albumin level, and PDA size were independent risk factors influencing the efficacy of NSAIDs (p < 0.05)." (PMID 37082702, 2023). "There were significant differences between the two groups in terms of: chorioamnionitis; multiple pregnancy; gestational age; use of indomethacin; use of inotropic agents; invasive or noninvasive ventilation; plasma albumin level, PDA size; Vmax." (PMID 37082702, 2023).
choroidal neovascularization (1 paper, 2021). An eye disorder described by the growth of new blood vessels that originate from the choroid through a break in the Bruch membrane into the sub–retinal pigment epithelium (sub-RPE) or subretinal space. "Isolectin-B4, Ki67, HIF-1α, VEGF, NMDAR1, and albumin were assessed by immunofluorescence (IF), Western blot (WB), Optical coherence tomography (OCT), and fluorescein angiography (FA) to evaluate retinal structure, fluorescein leakage, and choroidal neovascularization (CNV)." (PMID 34502266, 2021).
chronic gastritis (1 paper, 2020). Inflammation of the stomach that is chronic in nature. "In multivariate analysis, male gender, urea and albumin levels were associated with the presence of pathological chronic gastritis." (PMID 33092560, 2020). "However, the increased albumin level in our patients increased the risk of chronic gastritis by 8.83-fold." (PMID 33092560, 2020). "Men gender (p = 0.030), urea (p = 0.014) and albumin levels (p = 0.048) influenced the presence of pathological chronic gastritis." (PMID 33092560, 2020). "In our patients with chronic gastritis, sodium and LDL cholesterol, total protein and albumin levels were higher and urea and ferritin levels were lower." (PMID 33092560, 2020).
coagulation abnormalities (1 paper, 2020). "Abnormal platelet numbers suggest coagulation abnormalities, and atypical albumin and bilirubin levels reflect organ dysfunction." (PMID 33396578, 2020).
communication disorder (1 paper, 2024). A disorder characterized by an individual's inability to comprehend or share ideas or feelings because of an impairment in language, speech, or hearing. "Motor function, serum alkaline phosphatase, serum albumin, and prothrombin activity are independent risk factors associated with the prognosis of communication disorders after CPVS." (PMID 38587684, 2024). "In this study involving children with CP, the serum albumin levels were significantly higher in the group with good prognosis than in the group with poor prognosis of communication disorders after CPVS." (PMID 38587684, 2024). "Multivariate analysis revealed that motor dysfunction, serum ALP, serum albumin, and PTA were the influential factors for poor prognosis of communication disorders in children with CP after CPVS." (PMID 38587684, 2024).
congenital nephrosis (1 paper, 2020). "Of the sample, congenital nephrosis (55.8%), and low albumin level (96.5%) were common characteristics among children undergoing peritoneal dialysis in our center." (PMID 31996157, 2020). "Older children, congenital nephrosis, height and weight below the 3rd percentile, low albumin level, and long duration of antibiotic therapy were associated with a higher rate of peritonitis." (PMID 31996157, 2020).
Creutzfeldt Jacob disease (1 paper, 2015). A rare transmittable degenerative disorder of the brain caused by prions. "Following concerns for transmission of Creutzfeldt-Jacob disease, human serum albumin was removed from Eprex and replaced by polysorbate 80 and glycine." (PMID 26240773, 2015).
cryoglobulinemia (1 paper, 2011). Cryoglobulinemia is a type of vasculitis that is caused by abnormal proteins (antibodies) in the blood called 'cryoglobulins.' At cold temperatures, these proteins become solid or gel-like, which can block blood vessels and cause a variety of health problems. "Multivariate analyses did not identify a significant correlation between any of the anthropometric or laboratory variables studied (age, BMI, cryoglobulinemia, HCV RNA level, ALT, albumin, glucose) and changes of autonomic function indices during antiviral treatment." (PMID 22087127, 2011).